B3GLCT (beta 3-glucosyltransferase)
Description:
Beta-1,3-glucosyltransferase involved in one of the two pathways responsible for protein O-linked fucosylation, a unique post-translational modification of cysteine-knotted proteins that regulates various biological processes. This pathway targets proteins with Thrombospondin type-1 (TSP1) repeats (TSR) in the endoplasmic reticulum. It starts with POFUT2, which attaches fucose via an O-glycosidic bond to a conserved serine or threonine residue. B3GLCT extends this modification by transferring a glucose molecule from UDP-glucose to the fucose.
Synonyms: Beta3Glc-T; B3GALTL; B3GTL; B3Glc-T; Gal-T
Tractability: Antibody: UniProt predicts a signal peptide or a membrane-spanning region. PROTAC: ubiquitination databases record sites on it; its protein half-life has been measured.
Gene: Protein-coding gene on chromosome 13 (31,199,975 to 31,332,276, forward strand). Ensembl gene ENSG00000187676.
Subcellular location: Endoplasmic reticulum membrane
Pathways (Reactome):
Disease: Defective B3GALTL causes PpS
Metabolism of proteins: O-glycosylation of TSR domain-containing proteins
Gene Ontology:
Molecular function: O-fucosylpeptide 3-beta-glucosyltransferase activity; acetylglucosaminyltransferase activity; glycosyltransferase activity
Biological process: protein O-linked glycosylation via fucose
Cellular component: endoplasmic reticulum membrane; membrane
Genetic constraint (gnomAD): Loss-of-function variants: 30 observed, 36.69 expected, observed/expected ratio (o/e) 0.82, 90% interval 0.61 to 1.11. The upper end of that interval is the gene's LOEUF score, 1.11, which puts it in group 4 of 6, group 1 being the genes least tolerant of losing a copy. Missense variants: 410 observed, 404.73 expected, observed/expected ratio (o/e) 1.01, 90% interval 0.93 to 1.1. Synonymous variants: 158 observed, 153.62 expected, observed/expected ratio (o/e) 1.03, 90% interval 0.9 to 1.17.
Gene-disease validity (ClinGen):
ClinGen rates the evidence that B3GLCT causes each of these diseases.
Peters plus syndrome (autosomal recessive): Definitive.
Homologues: Orthologues: chimpanzee B3GLCT (98% identical), macaque B3GLCT (94% identical), dog B3GLCT (90% identical), guinea pig B3GLCT (86% identical), pig B3GLCT (85% identical), rat B3glct (84% identical), mouse B3glct (84% identical), rabbit B3GLCT (78% identical), tropical clawed frog b3glct (64% identical), zebrafish b3glcta (60% identical), zebrafish b3glctb (55% identical), Drosophila melanogaster CG9109 (35% identical), and 1 more. Paralogues in human: LFNG (15% identical), RFNG (14% identical), MFNG (13% identical).
Diseases named in the same sentence as B3GLCT in open-access papers:
B3GLCT is named in the same sentence as 15 diseases in open-access papers, as found by Europe PMC text mining. Sharing a sentence is not in itself a finding about the gene and the disease. The quoted sentences say what the papers report.
Peters plus syndrome (19 papers, 2009 to 2024). "Weh E., Takeuchi H., Muheisen S., Haltiwanger R.S., Semina E.V.Functional characterization of zebrafish orthologs of the human Beta 3-Glucosyltransferase B3GLCT gene mutated in Peters Plus Syndrome." (PMID 35087996, 2020). "Additional studies of the outcomes of b3glct deficiency in zebrafish may provide insight into disease mechanisms and/or suggest potential modifiers of Peters Plus Syndrome in humans." (PMID 28926587, 2017). "Enzymatic deficiency of O-Fucose-specific β-1,3-N-glucosyltransferase (B3GALTL, sometimes referred to as B3GLCT or B3GTL) [OMIM:261540], also known as Peters plus syndrome, is a rare AR disorder that presents with syndromic developmental defects mostly affecting the eye." (PMID 37239976, 2023).
depression (2 papers, 2021 to 2024). "One pathway classically related to glycosylation was recently reported to play a role in the genetics of depression: B3GALTL (Beta 3-Glucosyltransferase) was found to be associated with suicide behavior in a proteome-wide association study on depression." (PMID 38878077, 2024).
glycosylation disorder (1 paper, 2019). "PPS, a very rare subtype of ASD, is a glycosylation disorder, where the dysfunctional B3GLCT gene product, O-fucose-specific β-1,3-glucosyltransferase, is ineffective in providing a noncanonical quality control system for proper protein folding in cells." (PMID 31795264, 2019).
B3GLCT also shares sentences with these, for which no sentence is quoted: developmental delay (2 papers); age-related macular degeneration (1); Alzheimer disease (1); bipolar disorder (1); congenital glycosylation disorder (1); diabetes mellitus (1); glaucoma (1); polycystic kidneys (1); polycystic ovaries (1); rheumatoid arthritis (1); schizophrenia (1); tumour (1).